EGFR (epidermal growth factor receptor)
Diseases named in the same sentence as EGFR in open-access papers (continued):
Sharing a sentence is not in itself a finding about the gene and the disease.
lung adenocarcinoma (continued). "The negative effect on tumorigenesis is mediated by EGFR since the expression of a palmitoylation-resistant mutant form of EGFR also inhibits Kras-driven lung adenocarcinoma." (PMID 34610265, 2021). "A total of 10,046 patients with EGFR-mutant advanced lung adenocarcinoma initiated first-line EGFR-TKI therapy with 3,695 patients who received gefitinib, 3,310 who received erlotinib and 3,041 who received afatinib." (PMID 34434112, 2021). "Together, this indicated that TKIs induced the antitumor activity through the inhibition of EGFR-related signaling in the EGFR-mutant lung adenocarcinoma cells." (PMID 34367939, 2021). "A 67-year-old Asian woman with EGFR 19del mutant lung adenocarcinoma and brain metastases was treated with almonertinib 110 mg po qd as a first-line treatment." (PMID 34630120, 2021). "Activating mutations of epidermal growth factor receptor (EGFR)—exon 19 deletion and exon 21 substitution are present in 10–36% of Caucasian patients with adenocarcinoma of the lung." (PMID 34830123, 2021). "Roughly 40–50% of lung adenocarcinomas diagnosed in China harbor the mutant epidermal growth factor receptor (EGFR) gene." (PMID 33916930, 2021). "Immune checkpoint inhibitors have achieved breakthrough efficacy in treating lung adenocarcinoma (LUAD) with wild-type epidermal growth factor receptor (EGFR), leading to the revision of the treatment guidelines." (PMID 34178613, 2021). "Case Report: A 72-year-old patient was diagnosed with a lung adenocarcinoma in February 2018 (EGFR-, ALK-, and PDL1 90%)." (PMID 34046006, 2021). "As a result of a detailed examination, she was diagnosed with stage IV lung adenocarcinoma expressing L858R-mutant epidermal growth factor receptor (EGFR)." (PMID 34107910, 2021). "Significant advances in the molecularly targeted therapies have been made to treat lung adenocarcinoma patients harboring mutant EGFR, ALK, RET,ROS1, BRAF, MET, NTRK-1 & 2, ERBB2, and FGFR3." (PMID 33796225, 2021). "Our findings warrant future studies to investigate CD8 T-cell counts in EGFR mutant lung adenocarcinoma responders of such immunotherapies in clinical trials to determine how it affects treatment outcomes." (PMID 35052732, 2021). "Our findings demonstrate that targeting YAP‐p62 will be helpful to suppress the EGFR‐TKI resistance of lung adenocarcinoma." (PMID 33486901, 2021). "This study aimed to clarify novel predictors of immunotherapy following EGFR‐TKI resistance in lung adenocarcinoma, especially regarding micro RNA (miRNA)." (PMID 33305905, 2021). "Future studies are required to fully decipher the potential differences between MAPK signaling activation at different levels of the pathway in the context of EGFR-mutant lung adenocarcinoma." (PMID 34921211, 2021). "Some studies have revealed that EGFR and KRAS mutations are mutually exclusive in lung adenocarcinoma, the mechanisms of which need to be investigated in more depth." (PMID 34447695, 2021). "Tyrosine 1068, 1086, and 1143 of EGFR were characterized to reflect EGFR activation in lung adenocarcinoma, and were irreplaceable for EGFR-related signaling." (PMID 34367939, 2021). "Here we showed that two WWOX SNPs, rs3764340 C/G and rs73569323 C/T, are highly associated with large tumor size and invasion of adjacent tissues in patients with EGFR-L858R mutant lung adenocarcinoma." (PMID 34948746, 2021). "The recent evolution of targeted therapies has helped prolong the OS of patients with EGFR-mutant advanced lung adenocarcinoma." (PMID 34847914, 2021). "It restores sensitivity to EGFR-TKIs in lung adenocarcinoma with primary and acquired EGFR-TKI-resistance." (PMID 34202980, 2021). "In our previous study analyzing the clinical outcomes of completely resected stage III lung adenocarcinoma harboring mutant EGFR, more than half of all cases ultimately developed distant metastasis." (PMID 33916930, 2021).
lung adenocarcinoma (continued). "This, therefore, indicated that the necroptosis was critical for TKI-induced antitumor activity in the EGFR-mutant lung adenocarcinomas." (PMID 34367939, 2021). "PHGDH acts on serine biosynthesis, and the inhibition of PHGDH was proposed to treat epidermal growth factor receptor-tyrosine kinase inhibitor (EGFR-TKI)-resistant lung adenocarcinoma." (PMID 33500332, 2021). "In sum, inactivated c-Src by dasatinib sealed the phosphorylated tyrosine 1068, 1086, and 1145 of EGFR to inhibit the survival pathway to sensitize EGFR-mutant lung adenocarcinoma to TKI." (PMID 34367939, 2021). "We further identified that HDAC1 robustly interacts with EGFR in lung adenocarcinoma cell lines, as well as HEK293T cells, by the high-confidence K-CLASP technique and co-immunoprecipitation." (PMID 33976119, 2021). "We sought to identify molecular mechanisms of lower efficacy of immunotherapy in epidermal growth factor receptor (EGFR) mutant lung adenocarcinoma and the differences in those mechanisms with the emergence of tyrosine kinase inhibitor (TKI)-resistance." (PMID 34638461, 2021). "First-line targeted therapy with tyrosine kinase inhibitor (TKI) is recommended as the standard treatment for stage IV EGFR-mutant lung adenocarcinoma." (PMID 34676174, 2021). "In clinical practice, the mutation/expression of epidermal growth factor receptor (EGFR) and anaplastic lymphoma kinase (ALK) in first-line targeted therapy improves the survival rate of patients with lung adenocarcinoma." (PMID 33446784, 2021). "Patients with newly diagnosed lung adenocarcinoma commonly undergo sequential molecular testing (for EGFR, ALK, ROS1)." (PMID 34918209, 2021). "TKIs suppressed EGFR-related signaling to yield cell deaths of lung adenocarcinoma by necroptosis and intrinsic apoptosis." (PMID 34367939, 2021). "Genotyping epidermal growth factor receptor (EGFR) is an essential process to indicate lung adenocarcinoma patients for the most appropriate treatment." (PMID 34294857, 2021). "Our dataset also includes ~1000 novel HLA class I interaction partners and hundreds of Class I-presented immunopeptides in EGFR mutant lung adenocarcinoma." (PMID 34638461, 2021). "Together, the phosphorylation of tyrosine 1068, 1086, and 1148 was reflective of the EGFR activation accompanied by the EGFR-related signaling in lung adenocarcinoma." (PMID 34367939, 2021). "We extracted ENO1 and EGFR data from 34 tumors and found that both were notably upregulated in diverse cancer types, especially lung adenocarcinoma and lung squamous carcinoma tissues." (PMID 34627260, 2021). "A representative example of this bimodal distribution was shown by the top ranking comparison, i.e., lung tumors driven by mutations of either the EGFR or the KRAS oncogenes, which characterize two distinct genomic subtypes of lung adenocarcinoma." (PMID 34344431, 2021). "In summary, the results of our present study indicate that intra‐tumoral CD8‐positive T cells are decreased in lung adenocarcinoma patients acquiring EGFR‐TKI resistance when levels of miR‐1 are raised." (PMID 33305905, 2021). "Given this genetic background, we used HN6 showing the highest expression of EGFR among all HNSCC cell lines and HCC827 cells, lung adenocarcinoma cell lines harboring deletion of E746-A750 in EGFR." (PMID 34725466, 2021). "All the patients were diagnosed with stage IIIB-IV lung adenocarcinoma and were EGFR-TKI-naive before receiving mefatinib therapy." (PMID 34719670, 2021). "The Class I-presented immunopeptidome identified in this dataset is a unique resource for the demonstration of actual peptides presented by Class I proteins in EGFR mutant lung adenocarcinoma cells." (PMID 34638461, 2021). "Although several studies have investigated relationships between CT imaging features and EGFR mutation and ALK status, such associations in lung adenocarcinoma are conflicting due to the small sample sizes." (PMID 33707479, 2021).
lung adenocarcinoma (continued). "In this study, we tried to reveal the effect of autophagy adaptor p62 which is accumulated by autophagy inhibitor in EGFR‐TKI‐resistant lung adenocarcinoma." (PMID 33486901, 2021). "It has been reported that TKIs induced apoptosis through the inhibition of survival pathways in EGFR-mutant lung adenocarcinoma." (PMID 34367939, 2021). "Third, ALK rearrangements are almost always mutually exclusive with other driver mutations, such as EGFR and KRAS mutations in lung adenocarcinoma." (PMID 33738250, 2021). "In this prospective study, we demonstrated that longitudinal assessment of ctDNA can be used to predict clinical outcomes in patients with EGFR-mutant lung adenocarcinoma treated with osimertinib." (PMID 34283064, 2021). "Mutations in epidermal growth factor receptor (EGFR) and rearrangements in anaplastic lymphoma kinase (ALK) and c‐ros oncogene 1 (ROS1) have emerged as effective therapeutic targets for advanced lung adenocarcinoma." (PMID 33963680, 2021). "We identified that p62 has oncogenic functions that induce cell proliferation and invasion of EGFR‐TKI‐resistant lung adenocarcinoma." (PMID 33486901, 2021). "Our previous research found that TAZ was an oncogene closely associated with the therapeutic effect of cisplatin and EGFR-TKIs in lung adenocarcinoma." (PMID 33413409, 2021). "We have conducted the study to evaluate immunohistochemistry’s performance in detecting the E746-A750 deletion in exon 19 of the EGFR gene in primary lung adenocarcinoma cases." (PMID 34181354, 2021). "We suggest that targeting YAP‐p62 signaling axis can be useful to overcome the EGFR‐TKI resistance in lung adenocarcinoma." (PMID 33486901, 2021). "The histological transformation of lung adenocarcinoma to SCLC has been found in 3–14% of patients treated with EGFR-TKIs." (PMID 34094904, 2021). "The pan-ERBB inhibitor, afatinib, is a second-generation TKI which also demonstrated longer PFS in metastatic EGFR-mutated lung adenocarcinoma compared to standard chemotherapy." (PMID 34202748, 2021). "EGFR-mutant lung adenocarcinoma cells with acquired resistance to third-generation EGFR inhibitors are sensitive to AKIs." (PMID 34956905, 2021). "Activating mutations in epidermal growth factor receptor (EGFR) and anaplastic lymphoma kinase (ALK) rearrangement are the major driving force for lung adenocarcinoma while most squamous cell carcinomas display somatic mutation of p534,6–8." (PMID 33833226, 2021). "The loss of MHC-I antigen presentation and components of the APM was also described among EGFR-mutant lung adenocarcinoma with SCLC transformation." (PMID 34162872, 2021). "The epidermal growth factor receptor (EGFR) pathway is involved in the progression of various cancers, and its mutation is frequently seen in lung adenocarcinomas." (PMID 34926310, 2021). "In the present study, we evaluated the effects of WWOX polymorphisms, including rs11545028, rs12918952, rs3764340, rs73569323 and rs383362, on lung adenocarcinoma with wild-type and mutant EGFR." (PMID 34948746, 2021). "The proposed model in this study showed the potential to help clinicians identify suitable advanced patients with lung adenocarcinoma for EGFR‐targeted therapy." (PMID 34367993, 2021). "The epidermal growth factor receptor (EGFR) is a primary target of molecular targeted therapy for lung adenocarcinoma (LUAD)." (PMID 34447695, 2021). "Our study identified a DNA methylation marker for predicting drug response in lung adenocarcinoma and provides insight into the epigenetic regulation of IR to EGFR-TKIs." (PMID 34036228, 2021). "Recently, miR-3613-3p was reported to regulate genes of EGFR signaling pathway in the epithelial-mesenchymal transition of lung adenocarcinoma." (PMID 33494814, 2021). "This large-scale unbiased proteomics study provides novel insights and potential mechanisms of immune evasion of EGFR mutant lung adenocarcinoma." (PMID 34638461, 2021).
lung adenocarcinoma (continued). "In this prospective study of 25 patients with EGFR-mutant lung adenocarcinoma receiving osimertinib, ctDNA progression predated radiographic progression by 118 days in 11 of 20 patients with disease progression." (PMID 34283064, 2021). "The paradigm shift in treating lung adenocarcinoma with EGFR-targeted therapy is a major success in precision medicine." (PMID 34036228, 2021). "Several case reports have revealed the efficacies of EGFR-TKIs in advanced lung adenocarcinoma (LUAD) with EGFR-KDD but yielded variable antitumor responses." (PMID 33898306, 2021). "The addition of dasatinib consistently had the marked impacts on promoting the response of the EGFR-mutant lung adenocarcinoma to gefitinib." (PMID 34367939, 2021). "Here, we employed large-scale MS-based proteogenomic profiling to identify potential immunogenic human leukocyte antigen (HLA) class I-presented peptides in melanoma and EGFR-mutant lung adenocarcinoma." (PMID 34391887, 2021). "In patient-derived, EGFR-mutant lung adenocarcinoma cells that were resistant to osimertinib (growth inhibition of 81 ± 15%), nivolumab and atezolizumab significantly inhibited the growth by (65 ± 18%) and (57 ± 13%), respectively, P < 0.05)." (PMID 34488906, 2021). "Integration of existing ICI therapies as well as novel immunotherapies in EGFR mutant lung adenocarcinoma are unmet needs." (PMID 34638461, 2021). "This modification activates the EGFR–Akt signaling pathway, which inhibits serum deprivation–induced cell death in a human lung adenocarcinoma cell line." (PMID 33705793, 2021). "In summary, primary surgical resection improves survival of lung adenocarcinoma patients with intraoperatively-confirmed occult pleural metastases followed by EGFR-TKIs." (PMID 33954108, 2021). "In sum, EGFR palmitoylation appears to be required for PI3K–AKT–Myc signalling in Kras-mutant lung adenocarcinoma, revealing DHHC20 inhibition as a therapeutic vulnerability in the PI3K–AKT pathway." (PMID 34610265, 2021). "Epidermal growth factor receptor (EGFR) mutation is one of the most important driver mutations for lung adenocarcinoma and EGFR-tyrosine kinase inhibitor (TKI) will benefit those patients with sensitive EGFR mutations." (PMID 33910272, 2021). "We also confirmed that the expressions of p62 and YAP have a positive correlation in EGFR‐mutant lung adenocarcinoma patients." (PMID 33486901, 2021). "Based on this, we proposed to utilize radiomics to predict the first progression sites of first-line TKI treatment of EGFR-mutant lung adenocarcinoma patients." (PMID 34676174, 2021). "Ethnicity differences are known to contribute to different rates of EGFR and KRAS mutation in lung adenocarcinoma." (PMID 34026636, 2021). "The two most common druggable targets are epidermal growth factor receptor (EGFR) mutations and anaplastic lymphoma kinase (ALK) rearrangement in lung adenocarcinomas." (PMID 33707479, 2021). "Patients with primary lung adenocarcinoma with -216T/T and -216G/T had a higher EGFR expression compared to those with-216G/G41–43." (PMID 34168192, 2021). "The purpose of this study was to develop a deep learning-based system to automatically predict epidermal growth factor receptor (EGFR) mutant lung adenocarcinoma in 18F-fluorodeoxyglucose (FDG) positron emission tomography/computed tomography (PET/CT)." (PMID 34367993, 2021). "Mutational profiling of lung adenocarcinoma patients reveals Kirsten rat sarcoma viral oncogene (KRAS), epidermal growth factor receptor (EGFR), and anaplastic lymphoma kinase (ALK) as the most prominent oncogenic drivers." (PMID 34073823, 2021). "PPARγ agonist efatutazone and gefitinib have been indicated to synergistically inhibit the proliferation of EGFR-TKI-resistant lung adenocarcinoma cells via the PPARγ/PTEN/Akt pathway." (PMID 34889713, 2021). "Surprisingly, EGFR signaling was different in the capability to maintain tumor growth in the different lung adenocarcinoma cells." (PMID 34367939, 2021).
lung adenocarcinoma (continued). "Surprisingly, blocking c-Src activation through dasatinib was able to inhibit the EGFR survival signaling by sealing tyrosine 1068, 1086, and 1145 of EGFR, which in turn increased the antitumor activity of TKIs in EGFR-mutant lung adenocarcinoma." (PMID 34367939, 2021). "Herein, we reported the case of a 69-year-old woman diagnosed with pneumonia-type lung adenocarcinoma with EGFR 19Del who had a marked response to gefitinib initially but developed active pulmonary TB." (PMID 33663064, 2021). "Collectively, c-Src inactivation by dasatinib administration sensitizes EGFR-mutant lung adenocarcinoma to TKIs." (PMID 34367939, 2021). "Here we found that HDAC1-EGFR interaction patterns change in lung adenocarcinoma cell lines with different EGFR backgrounds, albeit to varying extents." (PMID 33976119, 2021). "We initially investigated the role of forkhead box protein P3-positive (Foxp3+) regulatory T cells (Tregs) in EGFR-mutant lung adenocarcinomas." (PMID 34494649, 2021). "We reported a case of EGFR-mutant lung adenocarcinoma (mimicking pulmonary infections) that coexisted with pulmonary tuberculosis during the course of the disease." (PMID 33663064, 2021). "We established three patient-derived xenograft (PDX) models of lung adenocarcinoma from the drug refractory tumors of patients who developed resistance to single-agent EGFR TKI therapy." (PMID 34516823, 2021). "We firstly revealed that intra‐tumoral CD8‐positive T cells are decreased in lung adenocarcinoma patients acquiring EGFR‐TKI resistance when levels of miR‐1 are raised." (PMID 33305905, 2021). "We retrospectively collected data of 137 EGFR-mutant patients with advanced lung adenocarcinoma who underwent next-generation sequencing in our hospital in 2018." (PMID 34485120, 2021). "In another study of 111 patients with EGFR‐mutant lung adenocarcinoma, the acquired T790M‐mutant group (n = 58, 52.3%) had a significantly longer overall survival (p = 0.010) compared to patients without T790M mutation." (PMID 33529490, 2021). "In this study, we aimed to determine the clinical implications of Romo1 expression in patients with epidermal growth factor receptor (EGFR)-mutant lung adenocarcinoma treated with first-line tyrosine kinase inhibitors (TKIs)." (PMID 34956890, 2021). "To examine in more detail the differentially active domains that we identified, we focused on the comparison between KRAS-driven and EGFR-driven lung adenocarcinoma, which exhibited the highest AUC ratio." (PMID 34344431, 2021). "(a) Overview of representative somatic alterations, protein expression profiles, MAPK pathway activity, and neuroendocrine differentiation in small cell lung cancer (SCLC), lung adenocarcinoma (LUAD), and transformed SCLC from EGFR-mutated LUAD." (PMID 34121659, 2021). "Excessive protein levels due to gene amplification or increased-transcription are the most common EGFR perturbations found in gastrointestinal and lung adenocarcinoma as well as in cholangiocarcinoma." (PMID 34096503, 2021). "EGFR mutations are the most common type of mutation in lung adenocarcinoma (LUAD), and the therapeutic strategies and prognoses of patients have been greatly improved with advances in EGFR-TKIs." (PMID 34330894, 2021). "Patients with EGFR wild-type lung SCC and EGFR-mutant lung adenocarcinoma were consecutively enrolled as controls, and next-generation sequencing (NGS) was performed." (PMID 34195081, 2021). "EGFR serves as a biomarker for tumor pathological classification and targeted therapy in lung adenocarcinoma." (PMID 34950253, 2021). "It is another fact that anti-angiogenic drugs are not effective in combinations with other targeted therapies, with the exception of EGFR-mutant lung adenocarcinoma where EGFR inhibitors can be effectively combined with anti-VEGF antibody." (PMID 34257622, 2021). "The epidermal growth factor receptor (EGFR) gene is a prominent oncogene in multiple tumor entities including adenocarcinoma of the lung." (PMID 33048186, 2021).